LINC00189 (long independently transcribed non-coding RNA 189)
Synonyms: C21orf109; NCRNA00189
Gene: Long non-coding RNA gene on chromosome 21 (29,193,400 to 29,288,205, forward strand). Ensembl gene ENSG00000215533.
Diseases named in the same sentence as LINC00189 in open-access papers:
LINC00189 is named in the same sentence as 7 diseases in open-access papers, as found by Europe PMC text mining. Sharing a sentence is not in itself a finding about the gene and the disease. The quoted sentences say what the papers report.
cervical cancer (1 paper, 2021). A primary or metastatic malignant neoplasm involving the cervix. "For example, LINC00189 has been reported to be associated with several cancers, including ovarian cancer, cervical cancer, clear cell renal cell carcinoma, and urinary bladder cancer." (PMID 33708773, 2021).
melanoma (1 paper, 2022). A malignant, usually aggressive tumor composed of atypical, neoplastic melanocytes. "The prognostic signature based on the OS-ireRNAs included AC009495.2, LINC02446, LINC00189, RSRP1, CUTALP, CMAHP and MOSMO, and accurately predicted the prognosis of melanoma patients, especially for those who survived for more than 3 years." (PMID 36338651, 2022).
cancer (3 papers, 2016 to 2021). A tumor composed of atypical neoplastic, often pleomorphic cells that invade other tissues. "Some of them are cancer related, such as POU2F3, NKD1 and CYP2C8, while LINC00189, GCC2 and OR9Q1 genes are rarely reported in human diseases." (PMID 27602771, 2016). "Some of them were commonly investigated in cancer, while others were rarely reported, such as GCC2 and LINC00189, which may hold significant role in regulating specific module networks." (PMID 27602771, 2016).
LINC00189 also shares sentences with these, for which no sentence is quoted: squamous cell carcinoma of urinary bladder (2 papers); clear cell renal cell carcinoma (1); ovarian carcinoma (1); urinary bladder cancer (1).